GZMB (granzyme B)
Diseases named in the same sentence as GZMB in open-access papers (continued):
Sharing a sentence is not in itself a finding about the gene and the disease.
tumor (continued). "Furthermore, intratumoral injection of CuS‐MΦ induced remarkably anti‐tumor immunity via decreasing other immunosuppressive cell subsets including Treg cells and MDSCs, increasing tumor‐infiltrating IFN‐γ‐positive CD8+ T cells and Granzyme B‐positive CD8+ T cells, as well as activating DCs." (PMID 37323705, 2022). "The general activation of NK cells upon coculture with tumor cells may also partially explain the minimal, non-significant differences in secretion levels observed for some cytokines (e.g., IL-10, sFas-L, and granzyme B) upon comparison of MOCK and CAR-expressing NK-92 cells." (PMID 34804035, 2021). "Similarly, expression of the granzyme B T-cell activity marker and immune checkpoint proteins programmed death (PD)-1 and cytotoxic T-lymphocyte antigen (CTLA)-4 did not significantly decrease with either treatment based on immunohistochemistry or on protein levels in tumor lysates." (PMID 33731699, 2021). "Furthermore, antibody-mediated depletion of TGF-βi led to reduced tumour burden in spontaneously developing murine models of PDAC and critically, these tumours were more highly infiltrated with CD8+ T cells that expressed greater levels of granzyme B, IFNγ and TNFα." (PMID 32967079, 2020). "Although this same study did not link GzmB expression by CTLs to infiltration in established tumors, it prompted us to speculate that GzmB expressed by MDSCs at the onset of tumor development facilitates the transmigration of CD8+ T-cells by making the ECM leaky." (PMID 31212684, 2019). "Therefore, compared with KLRG1−CD8 T cells, higher expression of heparanase might contribute to the migration of KLRG1+CD8 T cells into tumor sites, where KLRG1+CD8 T cells could exert stronger cytotoxicity against tumor cells in FasL- and Granzyme B-dependent manners." (PMID 31664180, 2019). "Moreover, GZMB was also found inside tumor cells from treated rats, but not from control rats." (PMID 29983866, 2018). "HLA-DR+ CTLs expressed higher levels of the cytolytic proteins Granzyme B (p = 0.02) and Perforin (p = 0.03); Eomes (p = 0.03), involved in differentiation of effector CTLs and the inflammatory cytokine TNFα (p = 0.03), which also has anti-tumor properties, in comparison with HLA-DR negative CTLs." (PMID 30555458, 2018). "Interestingly however, the expression of granzyme B mRNA was higher in the micro-metastatic dLN, indicating the presence of a more functional CD8+ T cell population in micro-metastatic dLN which may control the metastatic tumor cells in these compartments." (PMID 25605488, 2015). "Additionally, in the center (CT) and the invasive margin (IM) of colorectal cancer tumors, CD3, CD8, GZMB (a marker for CD8-positive CTLs) and CD45RO (a marker for memory T cells) expression levels in each tumor region (CT and IM) were negatively correlated with tumor recurrence." (PMID 25289108, 2014). "Immunohistochemically, tumor cells are usually positive for CD3, CD8, CD56, TIA-1, granzyme B, and perforin, and negative for CD4 and CD5, consistent with the findings in our patient." (PMID 41328359, 2026). "The elevated Granzyme B and IFN-γ levels in intratumoral CD8+ T cells within the tumor microenvironment indicates not just numerical increases but functional enhancement of antitumor immunity." (PMID 41246348, 2025). "Quantitation using TCR network analysis further corroborated that cytotoxic CD4+ (GZMB+ and GZMK+) T cells were significantly overrepresented in clusters of tumor-blood matched TCRs over nonmatched TCRs in blood and tumor." (PMID 40299576, 2025). "Within tumor, blood-matched TCR phenotypes were predominantly not proliferating, but were instead consistently cytotoxic (GZMB+ and GZMK+ for CD4+, also GZMK+ and MAIT for CD8+), and also included noncytotoxic CXCL13+ CD4+ and Tregs as observed above." (PMID 40299576, 2025).
tumor (continued). "We detected unaltered IFN-γ and granzyme B production upon co-culture with B-ALL cells and similar numbers of tumour–NK cell conjugates irrespective of the presence or absence of Ly6a." (PMID 39642167, 2025). "Researchers found that SEMA6D is predominantly expressed by non-hematopoietic cells, especially tumor cells, and shows a strong negative correlation with CD8A, PDCD1, IFNG and GZMB." (PMID 41438751, 2025). "Most tumor-infiltrating CD8 + T cells are in the early effector memory stage of differentiation, co-expressing CD27, CD28, CD57, and Granzyme B, with little or no perforin." (PMID 39105866, 2024). "Unlike conventional T cell receptors (TCRs), CARs can directly recognize tumor cell surface antigens in a non-MHC-restricted manner and release perforin and granzyme B to induce apoptosis in tumor cells." (PMID 39882532, 2024). "Together, these data suggest that Axl expression on CD45+ cells, rather than on tumor cells, correlates with the increased infiltration of CD8+ and Granzyme B+ in HCC patients." (PMID 38673795, 2024). "Frequencies of gp100-specific CD8+ T-cells were also significantly increased in the lung of IAV-infected tumour-bearing mice expressing significantly higher levels of CD43 and GzmB compared to CD8+ T-cells from non-infected mice." (PMID 38271469, 2024). "Mice treated with the Ace-Resi group demonstrated increased frequencies and counts of CD8+ T cells, interferon gamma (IFNγ+) CD8+ T cells, and polyfunctional IFNγ+ GzmB+ CD8+ T cells compared to naïve tumor-bearing mice and healthy (no tumor) controls." (PMID 39399681, 2024). "In contrast to CD8+ T cells, in response to MC38 tumor cells, CD4+ T cells of the immunized mice did not secrete any increased amounts of GzmB in response to the tumor cells when compared to those T cells of unimmunized mice T cells." (PMID 38247803, 2024). "Differential gene expression analysis revealed that tumor-infiltrating γδ T cells, regardless of subtype, exhibited higher expression of KLF2 and GZMB." (PMID 39454432, 2024). "This resulted in reduced growth of CD73+ tumors, accompanied by higher levels of granzyme B. Furthermore, CD73-CAR-NK cells led to a prolonged arrest of tumor growth, persisting for nearly 50 days post-tumor implantation, unlike the other treatment groups." (PMID 38694508, 2024). "We observed that when the GSDME was depleted in the tumors, ORFV treatment was not able to recruit enough tumor-infiltrating CD8+, antigen-specific CD8+, and GzmB+CD8+ T cells, as compared to that in WT tumors." (PMID 36641456, 2023). "PancVAX2-induced CD4+ T cells did not express the cytotoxic effector molecule GzmB, suggesting that the CD4+ T cells were not directly cytolytic, as has been reported preclinically and clinically in a subset of tumor-reactive T cells." (PMID 38063199, 2023). "The co-culture system showed that tumor-infiltrating mast cells had a stronger inhibitory effect on CD8+ T-cell proliferation and granzyme-B secretion than non-tumor-derived mast cells." (PMID 37042867, 2023). "When LCMV-primed T cells and tumor cells were co-incubated, 5-NL increased the expression of TNF alpha (TNFα), GZMB and IL-2 in CD8+ T cells incubated with B16.GP33 but not B16 cells." (PMID 37582744, 2023). "Addition of the TGFβRII inhibitor SB431542 to OT-I:ID8-OVA-T4 co-cultures doubled the proportions of IFNγ+granzyme B+ OT-I cells, but did not impact upon OT-I T cell responses to ID8-OVA-N4 tumour cells." (PMID 35958566, 2022). "The absence of CXCR3 seems not to interfere with the ex vivo-specific lysis against tumor cells (OT-I CD8 T cells/OVA-expressing tumor cells) nor with the IFNγ, TNFα or Granzyme B expression." (PMID 36429101, 2022). "FC did not correlate with any of the markers of local tumour inflammation (Klintrup–Mäkinen grade, lymphocytes, neutrophils, CD3, CD4, CD8, CD45, TIA-1, granzyme B and myeloperoxidase)." (PMID 35397505, 2022).
tumor (continued). "Of note, the expressions of GZMB and PRF1, which are essential effector molecules for NK cell cytotoxicity, are found significantly lower in tumor tissues compared with adjacent nontumor tissues of JORRP patients." (PMID 35350785, 2022). "We also found that the densities of NK cells, Th2 cells, CD8+Granzyme B+ T cells, and CD3+CD8+EOMES−PD-1− T cells, respectively, were significantly decreased in the peripheries compared to the tumor areas in ICC, but not DCC." (PMID 35346322, 2022). "On the contrary, PGRN+/PanCK+ tumor cells expressed no, or only low levels of MHCI, and infiltrating CD8+ and GzmB+ cells were scarce." (PMID 35013174, 2022). "However, in the generation and release of GzmB, the MDSCs were not given any additional stimulation other than the culture techniques used to generate the heterogenous cell population: conditioned media from Granulocyte-Macrophage Colony Stimulating Factor (GM-CSF) producing tumor cells." (PMID 35326588, 2022). "Although we found significantly higher numbers of tumor-specific CD8+ TILs in the background of lymphatic MHC-II knockout, we did not see significant differences in granzyme B positivity in these cells in vivo, as suggested by our in vitro data." (PMID 36362253, 2022). "CTLs can also be present but functionally inactive within the tumor microenvironment, as demonstrated by their limited and/or absent production of IL2, granzyme B (GrB), and IFNγ." (PMID 35207374, 2022). "Nevertheless, the effector cytokine production capacity post peptide restimulation in the periphery and at the tumor site was comparable between the SCR and PGC-1α overexpression groups in terms of IFNγ, TNFα, granzyme B, and IL-2 production (data not shown)." (PMID 32055005, 2021). "Immunofluorescence of PuMA lung sections from A673 EwS cells revealed the presence of Granzyme B in proximity to CD99-positive cells in NOD-SCID mice, but not NSG mice, at day 3 following tumor cell injection." (PMID 33828989, 2021). "However, in the B16F10 tumor model, which has also been shown to be partially responsive to anti-PD-1 antibody therapy, we and others did not observe a significant increase in granzyme B expression after the anti-PD-1 antibody treatment, despite an increased CD8+ cell number." (PMID 34832863, 2021). "Tumor cells were positive for CD3, CD8 (72.7%), CD56, CD103 (60%), granzyme B (81.8%), and TIA-1 (66.7%), while negative for CD20, CD10, PD-1, ALK, and EBER ISH." (PMID 34072328, 2021). "Notably, multiple cytotoxic effector-related molecules (i.e., CD107a, granzyme B, perforin, IFN-γ, and 4-1BB) were significantly upregulated in eNKs compared to their expression in PB-NKs, which suggested that NK cells could show enhanced anti-tumor cytotoxicity following ex vivo expansion." (PMID 34831019, 2021). "More importantly, CD8+ TIL from B16F10E-KO was much more strongly enriched with granzyme B+ T cells than B16F10E untreated or treated with anti-PD-1, with no further enrichment after PD-1 blockade in the former tumours." (PMID 34471106, 2021). "Dual ICB treatment also increased tumor-infiltrating CD8+ T cells, but did not increase the activity of CTLs, as gauged by granzyme B." (PMID 34873175, 2021). "The effector function of MC38 tumor-infiltrating CD8+ T cells, however, appeared largely unaffected as we detected no overt changes in Ki-67 and granzyme B (GzmB) expression and only a modest reduction of IFN-γ expression upon LSD1 depletion." (PMID 34819502, 2021). "There was no significant change in CD8+Ki67+, CD8+Granzyme B+, CD4+, and Foxp3+ (Treg) T cells compartment in the spleen and tumor." (PMID 32780726, 2020). "By contrast, surface markers of exhaustion (PD-1), activation (KLRG1, Granzyme B, perforin, Interferon gamma (IFNγ)) and death (CD95) were no different on tumor infiltrating CD8+ T cells between TM and vehicle treated mice." (PMID 32085796, 2020).
tumor (continued). "Despite finding increased numbers of tumor infiltrating CD8+ T cells, daily lactate administration did not change the percentage of GzmB+ cells or the GzmB, PD1 or CTLA intensity on CD8+ infiltrating cells." (PMID 33095157, 2020). "It has been shown that tumor-infiltrating Th17 lymphocytes display low expression of activation markers and effector functions, such as HLA-DR, CD25, granzyme B, and perforin, and they do not mediate direct cytotoxic activity targeted against cancer cells." (PMID 32148497, 2020). "From the tumor biopsy taken from a well-responding patient, we found a number of CD4+ T cells secreting granzyme B (GrB), but little to none were found in the biopsy obtained from the non-responder." (PMID 32036449, 2020). "The density of CD8+ cells in tumor tissue was not significantly increased, but the densities of both CD8+PD-1+ and CD8+Granzyme B+ cells increased significantly after vaccination." (PMID 32500232, 2020). "CD8+ T cells from tumor‐bearing mice lacking USP44 also were found to express markedly higher levels of TNFα and significantly higher levels of the effector molecule granzyme B than their wild‐type counterparts." (PMID 32644293, 2020). "The tumour tissues in YT F0, YT F5 and YT F7were positive for CD56, Granzyme B, Perforin but negative for TiA1." (PMID 30484952, 2019). "Granzyme B release was found to be increased compared to the negative controls in both NIC3 and NIC4 when TIL were co-cultured with tumor material." (PMID 31888734, 2019). "Conversely, while the addition of bsAb clearly enhanced the granzyme B release by Vδ1 T cells, it did not significantly alter PGE2 release by the tumor cells." (PMID 31555275, 2019). "In the majority of the tumor samples analyzed (68%), CD8+ cells were granzyme B negative, reflecting a state of anergy." (PMID 31412566, 2019). "To test the potential bioactivity of granzyme B and perforin expressed by CAR exosomes, we investigated their cytotoxic effect against human tumour cell lines and exosomes from non-transduced T cells, which served as the control." (PMID 31554797, 2019). "Tumor-infiltrating type I NKT cells expressed IFN-γ and granzyme B, but the authors did not compare the expression of these markers to that of type I NKT cells in normal mucosa." (PMID 29535734, 2018). "Similar to tumor, circulating HLA-DR+ CTLs express more IFN-γ and Granzyme B than HLA-DR negative CTLs." (PMID 30555458, 2018). "The dual therapy reduces PD-L1+ cells and facilitates non-redundant tumour infiltration of effector CD8+, CD4+ T cells, with increased IFN-γ, ICOS, granzyme B and perforin expression." (PMID 28345650, 2017). "We used surface staining against the B10/Breg markers CD5, CD1d and Granzyme B in combination with CD19 and were able to identify cells with a Breg phenotype in wild-type controls but not in tumor-bearing recipients of T and B cells (data not shown)." (PMID 27121060, 2016). "Immunohistochemical examination revealed that the tumour cells expressed T-cell receptor (TCR)-βF1, CD3, CD4, CD25, cytotoxic-related protein TIA1 and granzyme-B, but were negative for CD8, Foxp3, CD20, CD30 and CD56." (PMID 23302373, 2013). "Immunohistochemically, the tumor cells tend to express CD56, cytoplasmic CD3ε, CD2, cytotoxic granule proteins, granzyme B, and TIA-1 but not surface CD3." (PMID 23958352, 2013). "In their study, tumour cells expressed CD3, CD8 and granzyme-B, but were negative for EBV infection." (PMID 23302373, 2013). "While we show that the Mam-A2.4 specific CD8 T cells secreted more IFN-γ, TNF-α and Granzyme B compared to either the full-length or the other epitope Mam-A specific CD8 T cells, this adoptive T cell therapy failed to prevent tumor relapse." (PMID 22911764, 2012).
tumor (continued). "CD8+ T cells from the spleen of naïve and tumour-bearing mice were not capable of IFN-γ and granzyme B production." (PMID 20804550, 2010). "For both markers, there were either few or no infiltrates at all within the tumor epithelium (data not shown), indicating that the TIA-1+ and Granzyme B+ infiltrates were most likely T cells." (PMID 19641607, 2009). "However, splenic uPA–/– CD8+ T cells selectively upregulated IFN-γ production but showed no concurrent increase in GzmB or TNF-α levels, suggesting that CD8+ T cells cytotoxicity in this context was tumor microenvironment-dependent." (PMID 40959092, 2025). "Specifically, granzyme A (GZMA), granzyme B (GZMB), granzyme K (GZMK) and perforin-1 (PRF1) do not only induce apoptosis and modulate immune response within the tumor microenvironment (TME), but also have other diverse roles, such as potentially regulating homeostasis post-infection." (PMID 40002821, 2025). "CD8+/Granzyme B+/Ki67+ also trended higher in responders compared with nonresponders, whereas overall CD8+ cell density was comparable between responders and nonresponders in both the tumor and stromal compartments and in the total tumor." (PMID 40069763, 2025). "Although CD8_Exh cells still express some cytotoxic-related genes like GZMB and NKG7, their overall function is in a hyporesponsive state and may not effectively kill tumor cells." (PMID 41394809, 2025). "Compared with combination therapy with alisertib and anti-IgG, combination therapy with alisertib and anti–B7-H3 mAbs significantly increased the abundance of total CD3+ T cells, tumor-infiltrating CD8+ T cells, perforin+ cells and granzyme B+ cells but not total CD4+ T cells." (PMID 39928563, 2025). "In the tumor microenvironment (TME), 5%–30% of CD4+Foxp3+ Treg cells have been observed to highly express granzyme B—a feature absent in Treg cells from some mouse models—suggesting that granzyme B production enables Tregs to kill NK cells and CD8+ T cells." (PMID 40297580, 2025). "Furthermore, co-administration of siSb9, GzmB and anti-PD1 significantly induces the ratio of mature DCs, CD4+ and CD8+ T cells, as opposed to a pronounced decrease in Tregs in the tumor tissue of murine B16 model, which implies an activated immune system." (PMID 38966643, 2024). "However, unlike in the human tumor environment, the human-like CD8 GZMB+ clusters in mouse hardly expressed Lag3 or Klrb1." (PMID 38245530, 2024). "In addition, compared to Nb-BiTE or control group, Nb-TriTE induced higher GzmB and PRF1 secretion levels after incubation with FAP+ tumor cells, but no significant changes in FAP− HepG2 tumor cells." (PMID 38031188, 2023). "Notably, SMAD4 suppresses tumor metastasis and promotes antitumor immunity through up-regulated IFN-γ and granzyme B (GZMB) by non-SMAD in NK cells at early stages." (PMID 35461253, 2022). "DuoBody-CD3x5T4–induced TIL-mediated tumor cell kill was also associated with dose-dependent production of IFNγ and GZMB; no IFNγ and GZMB production was observed when DuoBody-CD3x5T4 was incubated with the 5T4− LU1 tumor sample, in line with the absence of kill." (PMID 36271507, 2022). "In addition, tumor-infiltrating CD8+IFN-γ+, CD8+Ki67+ and CD8+GzmB+ T cells were not significantly altered by each treatment in tumor." (PMID 35058524, 2022). "Thus, a virus-induced FBL3 tumor in mice, which is normally eliminated by CD8+ T cells, was eliminated by tumor-specific CD4+ T cells that were also shown to produce granzyme B, but only in the absence of CD8+ T cells and Tregs." (PMID 36159781, 2022). "At the same time, the expression of PD-1, Lag-3, CTLA-4, Tim-3, and Granzyme B on Tregs from cryo-thermal treated mice was decreased, and the expression of perforin, T-bet and IFN-γ in Tregs was not different from that in Tregs from tumor-bearing control mice." (PMID 34576115, 2021).